OR5V1 (olfactory receptor family 5 subfamily V member 1)
Description:
Odorant receptor.
Synonyms: hs6M1-21; 6M1-21
Tractability: Antibody: UniProt places it where antibodies can reach, with medium confidence; UniProt predicts a signal peptide or a membrane-spanning region; its Gene Ontology location is reachable by antibodies, with medium confidence.
Gene: Protein-coding gene on chromosome 6 (29,353,749 to 29,431,967, reverse strand). Ensembl gene ENSG00000243729.
Subcellular location: Cell membrane
Pathways (Reactome):
Sensory Perception: Expression and translocation of olfactory receptors
Gene Ontology:
Molecular function: G protein-coupled olfactory receptor activity; G protein-coupled receptor activity; olfactory receptor activity
Biological process: adenylate cyclase-activating G protein-coupled receptor signaling pathway; detection of chemical stimulus involved in sensory perception of smell; intracellular glucose homeostasis; G protein-coupled receptor signaling pathway
Cellular component: plasma membrane; membrane
Genetic constraint (gnomAD): Loss-of-function variants: 0 observed, 0.31 expected, observed/expected ratio (o/e) 0, 90% interval 0 to 1.86. That is too few expected variants to judge how well the gene tolerates losing a copy. Missense variants: 365 observed, 392.15 expected, observed/expected ratio (o/e) 0.93, 90% interval 0.85 to 1.01. Synonymous variants: 134 observed, 151.85 expected, observed/expected ratio (o/e) 0.88, 90% interval 0.77 to 1.02.
Homologues: Orthologues: chimpanzee OR5V1 (98% identical), macaque OR5V1 (94% identical), mouse Or5v1 (81% identical), mouse Or5v1b (81% identical), rat Or5v1b (80% identical), rabbit OR5V1 (76% identical). Paralogues in human: OR10C1 (50% identical), OR10A7 (48% identical), OR6Y1 (47% identical), OR13C3 (47% identical), OR10A4 (47% identical), OR2D3 (46% identical), OR13C4 (46% identical), OR13C9 (46% identical), OR13D1 (46% identical), OR2B2 (46% identical), OR2S2 (46% identical), OR2B6 (46% identical), and 80 more.
Diseases named in the same sentence as OR5V1 in open-access papers:
OR5V1 is named in the same sentence as 7 diseases in open-access papers, as found by Europe PMC text mining. Sharing a sentence is not in itself a finding about the gene and the disease. The quoted sentences say what the papers report.
autism (1 paper, 2022). Persistent deficits in social interaction and communication and interaction as well as a markedly restricted repertoire of activity and interest as well as repetitive patterns of behavior. "The olfactory receptor genes OR12D2 and OR5V1, which are involved in the olfactory signaling pathway, G alpha (s) signaling events, GPCR downstream signaling, and GPCR signaling and signal transduction together regulate the overall olfactory growth, behavior, and impairment associated with autism." (PMID 35215271, 2022).
malignancies (1 paper, 2023). "Conclusively, these researchers demonstrated the antitumor potential of OR5V1-redirected CAR-T against OR5V1-positive malignancies with negligible toxicities." (PMID 38146364, 2023).
neurodegenerative disease (1 paper, 2022). A disorder of the central nervous system characterized by gradual and progressive loss of neural tissue and neurologic function. "Although further refinement would be needed to attribute causality of the variant, OR5V1 represents an important biological candidate for MS susceptibility given the notable olfactory dysfunction among a number of neurodegenerative diseases." (PMID 36548255, 2022).
OR5V1 also shares sentences with these, for which no sentence is quoted: amyotrophic lateral sclerosis (1 paper); autism spectrum disorder (1); schizophrenia (1); systemic lupus erythematosus disease (1).